AKT2 (AKT serine/threonine kinase 2)
Diseases named in the same sentence as AKT2 in open-access papers (continued):
Sharing a sentence is not in itself a finding about the gene and the disease.
cancer (continued). "We enrolled a total of twelve patients across eight different cancer types, including six patients with non-AKT1 E17K mutations (AKT1 D323G, E40K, L52R; AKT2 E17K, L78-Q79ins(HANTFVIRCL); AKT3 E17K) in this signal-seeking pilot study." (PMID 35440569, 2022). "Opposing roles of Akt1 and Akt2 in cell cycle progression, migration and invasion have been detected in various types of human cancer." (PMID 34419139, 2021). "Hyperactivation of the PI3K-Akt pathway is frequently observed in human cancers and overgrowth disorders, while autosomal dominant inactivation of Akt2 leads to insulin resistance and diabetes." (PMID 34385319, 2021). "Nevertheless, both methods of estimation (% inhibition and ratios correlated with control) indicate that both triazolo[3,4-b]thiadiazole derivatives exhibited significant inhibitory activity against Akt1and Akt2 phosphorylation in all three cancer cell lines." (PMID 33916378, 2021). "Screening for the impact of other amplified cancer genes in HEK293 cells also demonstrated that EGFR, AKT2, CCND1, CCNE1, SKP2, and FGFR3 caused both increased abundance of phosphorylated ZFP36/TTP and ARE-post-transcriptional reporter activity." (PMID 34535639, 2021). "The mRNA expression level of AKT2 is higher in cancer tissues than that in adjacent normal tissues, and it was proven as miR-503 target by luciferase assay." (PMID 33762949, 2021). "In particular, genes known to be associated with cancer such as LAMC2, UBE2C, AKT2, AKT2, BOK, MAP4, and FANCD2 were noted to be aberrantly spliced, indicating that the aberrant expression of CPSF1 significantly altered the ASEs of oncogenes in each dataset." (PMID 32437477, 2020). "The functional role of AKT2 in the physiologically state and in cancer cells has been reported as opposing compared to AKT1." (PMID 32962206, 2020). "An increasing amount of evidence supports that AKT2 can be regarded as a prognostic indicator in cancer patients." (PMID 32873299, 2020). "In line with our data, other groups reported increased cell death and suppressed proliferation in CRC cell lines and further entities of cancer after AKT2 specific knockdown." (PMID 32962206, 2020). "AKT2 is one of the key molecules that involves in the insulin-induced signaling and the development of cancer." (PMID 32252758, 2020). "It was observed that the silencing of AKT2 suppressed the cancer stem cell populations (CD44high CD24low, ALDH1), mammosphere formation, invasive and migratory potential in MCF-10A and BT-549 cells." (PMID 33227065, 2020). "There are three Akt isoforms (Akt1, Akt2, Ak3) found in mammalian cells, each with a distinct role in cancer." (PMID 32012648, 2020). "AKT2 has been well studied in cancer and insulin-mediated signaling, and in our study we demonstrate the function of AKT2 in B lymphocytes." (PMID 32252758, 2020). "To pursue this line of investigation further, we explored the consequences of AKT2 silencing in three different cancer cell lines, and their CSC-like fractions (MDA-MB-231, HCT8, and MCF7)." (PMID 31357505, 2019). "This further supports the existence of cancer stem-like cell function, via both AKT2/mTOR pathway and MAPK pathway, in our resistant cell lines." (PMID 31608140, 2019). "In detail, higher expression levels of AKT1 and AKT2 negatively influenced overall patients' survival, and in particular, AKT2 expression levels defined a group of luminal B BC patients with shorter cancer-specific survival." (PMID 31781306, 2019). "Previous genetic studies in mice demonstrated that AKT1 deletion inhibited cancer development in various mouse models, whereas AKT2 deletion had limited effects on cancer development in mouse models." (PMID 31113871, 2019). "The PI3K/Akt signaling pathway is an attractive target in anti-cancer therapy, but unexpected combinational deletion of Akt1 and Akt2 in adult hepatocytes results in liver injury that promotes HCC in mice." (PMID 31488102, 2019).
cancer (continued). "After a decade-long hiatus, there has been a renewed interest on the dual role of Akt in cancer after it was discovered that the deletion of Akt1 gene in Akt2+/− mice potentiate inflammation-induced hepatic cancer." (PMID 31360736, 2019). "Shorter cancer-specific survival was recorded in luminal B patients displaying higher levels of AKT2 (p = 0.03)." (PMID 31781306, 2019). "Our data revealed that AKT1 and AKT2 isoforms are differentially expressed and, in some cases, differentially phosphorylated in specific cancer lineages and genetic backgrounds." (PMID 30012111, 2018). "Triciribine’s target of inhibition Akt, also known as protein kinase B (PKB), is a serine/threonine kinase that has three isolated isoforms: Akt1 (PKBα), Akt2 (PKBβ) and Akt3 (PKBγ), whereby Akt1 is specifically up-regulated in most cancers." (PMID 30323898, 2018). "All Akt isoforms are involved in the induction and progression of human cancer, but the Akt1 and Akt2 isoforms play different roles in certain cancers: Akt1 is critical for cancer induction and Akt2 for metastatic dissemination." (PMID 29440989, 2018). "In summary, we identified differential expression and phosphorylation of AKT1 and AKT2 isoforms in different cancer lineages and genetic backgrounds, including the selective activation by PIK3CA hotspot mutation H1047R of AKT2 but not AKT1." (PMID 30012111, 2018). "Many studies show that AKT2 is involved in cancer development and play a great role in cell cycle, apoptosis, proliferation and migration." (PMID 29050238, 2017). "Akt1 and Akt2 activities have been reported to play roles for G1/S and G2/M transition in cancer and other somatic cells." (PMID 28483982, 2017). "The knockdown of AKT2 expression strongly repressed cancer cell proliferation, invasion and migration, which mimicked the effects of miR-143-3p restoration." (PMID 28404925, 2017). "It was reported that in several human cancer cell lines, Akt1 localizes in cytoplasm and Akt2 colocalizes with mitochondria, while Akt3 localizes in both nuclear membrane and nucleus." (PMID 28483982, 2017). "The results suggest that miRNAs targeting AKT2 have an important role in carcinogenesis and are potential therapeutic agents for human cancer." (PMID 29050238, 2017). "Total AKT (Akt1, Akt2 and Akt3) increased during development of various cancers, but in contrast, Akt1 levels were seen to be diminished." (PMID 28659381, 2017). "The Akt2 inhibitor CCT-128930 has also been tested in cancer cell lines and resulted in cell cycle arrest, increased Annexin localization and autophagy markers, although these effects were seen at very high concentration of inhibitor." (PMID 27533079, 2016). "Early on, the concept of the simultaneous administration of anticancer drugs with inhibitors of Akt2 was advocated to overcome cell proliferation in the chemotherapeutic treatment of cancer." (PMID 28036396, 2016). "Upregulation of Akt2 in various human carcinomas, including ovarian, breast, and pancreatic, is a well-known tumorigenesis phenomenon." (PMID 28036396, 2016). "In spite of their similarity in primary structure and substrate specificity, Akt1 and Akt2 isoforms play opposite roles in cell migration and cancer cell metastasis." (PMID 25575302, 2015). "Down-regulation of AKT2 sensitizes cancer cells to anticancer drugs by affecting apoptosis pathway such as caspases-3, caspases-6, caspases-9, PARP and p38 activity, and chemoresistance proteins such as MDR1 and MRP1." (PMID 25951903, 2015). "In conclusion, we believe in the potential pharmacological impact of selective Akt2 inhibitors to decrease lung tumor growth as well as cell invasion and metastasis even true that Akt1 also play a role in cancer cell invasion." (PMID 26234648, 2015). "Further, the construct utilized by this study activates AKT1, and although it is thought that AKT2 and 3 isoforms can compensate, evidence suggests they play distinct roles in cancer progression." (PMID 25971410, 2015).
cancer (continued). "The log fold change of genes involved in important pathways in cancer in DLD-1 AKT2 KO versus AKT1 KO." (PMID 24760019, 2014). "The mutation of all three isoforms of Akt, AKT1/PKBα, AKT2/PKBβ and AKT3/PKBγ are also observed in multiple types of cancers." (PMID 25334061, 2014). "Especially, cancer gene AKT2 (19q13.2) was amplified in two carcinomas, and CDKN2C (1p33) was homozygously deleted in other two cases." (PMID 25502777, 2014). "The expression of AKT2 in the cancer tissues showed higher expression than it expression in adjacent normal gastric tissues (P = 0.034)." (PMID 25288334, 2014). "Especially, amplification of AKT2 was detected in two carcinomas and homozygous deletion of CDKN2C in other two cases." (PMID 25502777, 2014). "AKT1 regulates cell survival, and AKT3 plays a critical role in brain development, whereas, AKT2 is more important in cancer development and progression." (PMID 23468863, 2013). "We genotyped 8 potentially functional polymorphisms in AKT1, AKT2, PTEN and MTOR genes using the TaqMan method in a case-control study of 710 RCC patients and 760 cancer-free subjects." (PMID 23209702, 2012). "Activation of the Akt2 signaling pathway has been observed following exposure of diverse cancer cell types to various chemotherapeutic agents." (PMID 21686164, 2011). "The mechanism by which Akt2 inhibition confers chemosensitivity in these cancer cells is unclear, but it appears to involve the regulation of transcription factors and proapoptotic proteins, such as PUMA." (PMID 21686164, 2011). "MiR-184, which targets the AKT2 mRNA, is a naturally occurring inhibitor of this protein, and has potential value in miRNA mediated therapeutics for any form of cancer dependent on AKT2." (PMID 20409325, 2010). "Understanding the role of nsSNPs in AKT2 can facilitate the development of targeted therapies tailored to individual genetic profiles, ultimately improving patient outcomes and addressing the ongoing challenge of inhibitor resistance in cancer therapy." (PMID 41144441, 2025). "The AGC-kinase C-terminal domain, where R467W is located, plays a critical role in AKT2 regulation, and its destabilization may have broader implications on the signaling functions of AKT2 in cancer pathways." (PMID 41144441, 2025). "These mutations significantly disrupt key molecular mechanisms, including metal binding, loss of allosteric sites, and changes in post-translational modifications such as phosphorylation and glycosylation, potentially altering AKT2’s role in cellular signaling and contributing to cancer progression." (PMID 41144441, 2025). "miRNA-4716–3p and AKT2 3′ UTR SNP rs2304186 (C→A) predicted mRNA interaction could be studied comprehensively across all cancer types." (PMID 38577021, 2024). "AKT2 is crucial for cancer cells' invasion, metastasis, and survival." (PMID 38577021, 2024). "Furthermore, while both the AKT2 gene and miRNA-4716-3p are capable of differentiating between blood cancer patients and healthy individuals on their own, our findings indicated that the two combined exhibited improved diagnostic efficacy." (PMID 38577021, 2024). "AKT2 gene variations were associated with PCOS, T2D, and cancer." (PMID 37754255, 2023). "They mapped a part of the AKT2 pathway by means of a specific nanobody and confirmed that AKT2 and its hydrophobic motif could be considered as potential targets for cancer treatment." (PMID 35933373, 2022). "The relationship between miR-124 and cancer cells behavior could be realized through inhibition of AKT2—the well-known oncogene and the direct target of miR-124." (PMID 35668332, 2022).
cancer (continued). "Furthermore, the silencing of Akt2 in triple negative breast tumor cells reduces the population and the metastatic potential of cancer stem cells (CSCs)." (PMID 35743776, 2022). "Recent studies indicated that the process of EMT existing in a variety of cancer cells could be triggered by the phosphorylation of PCBP1 at Ser43 by Akt2 upon TGF-β stimulation." (PMID 35100974, 2022). "The miR-126-3p/AKT2 axis established following the interaction between platelets and cancer cells could have clinical implications." (PMID 35628294, 2022). "Accordingly, KEGG analysis revealed that AKT2 was significantly enriched in several cancer-related signaling pathways, suggesting that AKT2 may act as a cancer gene in childhood ALL." (PMID 34055775, 2021). "The AKT2/PI3K pathway is frequently activated in cancer cells and inhibits apoptosis." (PMID 33488754, 2020). "AKT2 was known as an oncogene to promote cancer development." (PMID 33015042, 2020). "However, it is well-known that Akt kinase exists in three different isoforms as Akt1, Akt2, and Akt3, and these display distinct functions in various cancers." (PMID 31252679, 2019). "We speculated that an effective therapy could consist of standard therapy in combination with AKT2 inhibition, to completely eradicate all cancer cells." (PMID 31357505, 2019). "However, it has three isoforms (Akt1, Akt2, and Akt3) and they perform distinct functions and even play contrasting roles in different cancers." (PMID 31252679, 2019). "AKT2 is a major downstream effector of the canonical PI3-K (phosphoinositide 3-kinase) pathway, which appears generally associated with acquisition of the malignant phenotype in cancer cells." (PMID 31357505, 2019). "We compared protein and phospho-protein levels of AKT1 and AKT2 across different cancer lineages." (PMID 30012111, 2018). "Increasing studies demonstrated AKT2 had an important role in cancers as an oncogene." (PMID 29050238, 2017). "In this study, estrogen and progesterone receptor positive (ER + /PR + ) IBH-6 and T47D cancer cells were stably modified to upregulate or downregulate specifically AKT1 or AKT2 isoforms and search for their specific effects on cell proliferation, adhesion and invasion." (PMID 28287129, 2017). "Akt1 among other subtypes of Akt (Akt2 and Akt3) is involved in various cancers." (PMID 29088809, 2017). "Additionally, they demonstrated that knockdown of cytoplasmic p21WAF1/KIP1 by siRNA in Akt2 overexpressed cancer cells notably increased paclitaxel-induced apoptosis." (PMID 27716272, 2016). "Several reports have described the overexpression of Akt2 in various human cancers including, prostate, ovarian, breast, and pancreatic, and thus its role in tumorigenesis, poor prognosis, and chemo- and radio-therapeutic resistance in cancer patients have been reported in recent investigations." (PMID 28036396, 2016). "In addition, recent studies have shown that down-regulation of Akt2 expression appeared to sensitize cancer cells to typical chemotherapeutic agents." (PMID 25951903, 2015). "The expression of AKT2, AKT3, PKM2 and HK2 were significantly lower in the miR-29b agomir group compared with the NC agomir group, suggesting that miR-29b agomir treatment down-regulated in vivo AKT2/3 levels and further inhibited cancer cell glycolysis via downregulation of PKM2 and HK2 expression." (PMID 26512921, 2015). "Moreover, AKT2 is a transcriptional regulatory target of Twist that acts downstream of Twist to promote cancer cell survival, migration, and invasion." (PMID 26515594, 2015).
cancer (continued). "Second, a decrease in mtDNAcn may promote cells to become resistant to apoptosis through the activation of phosphatidylinositol 3-kinase (PI3K)/Akt2 signaling, and resistance to apoptosis contributes to cancer progression." (PMID 26515605, 2015). "Therefore, depletion of mtDNA likely blocks apoptosis, and promotes survival and motility of cancer cells via Akt2 activation." (PMID 24086362, 2013). "Mutations of AKT2 have been sporadically reported in various human cancers, but none of these mutations occur at the corresponding position of the E17K in AKT1." (PMID 22666248, 2012). "Also, overexpression of AKT2 at the messenger level has been shown in breast and colon cancers and seems to correlate with cancer migration, invasion, and metastasis." (PMID 22666248, 2012). "AKT2 is amplified in certain cancers (e.g., 12.1% ovarian and 2.8% breast carcinomas)." (PMID 21422497, 2011). "Oncogenes such as MYC, AKT1, AKT2, cyclins CCNA2, CCNB1, CCNB2, CCNE1, CCNE2 and cyclin-dependent kinases CDK1 and CDK4, which were upregulated under androgen treatment, exhibited a significantly reduced expression following PVT1 knockdown, thereby modulating cancer-associated oncogenic pathways." (PMID 41792045, 2026). "Interestingly, AKT2 Ser128 was appeared in almost all of these identified pathways in CAFs #1 treated with defactinib (10 μM), and the upregulated CCTα Ser315/319/323 sites existed in choline metabolism in cancer (KEGG ID: hsa05231)." (PMID 38280862, 2024). "In addition, a therapy aimed at restoring the levels of MUL1 in those cancers may downregulate Akt2 and HIF-1α and achieve tumor regression, as seen in other models." (PMID 38139010, 2023). "Significant difference of Akt2 mRNA expression was also presented between four histologic grade groups (p = 0.001), and in the post-hoc test, Akt2 was found to be significantly increased in high-grade carcinoma than those in the normal mammary gland (p = 0.02)." (PMID 34359206, 2021). "Thus, AKT2 is considered a promising target for cancer-targeted therapy." (PMID 32873299, 2020). "In addition, Akt1 and Akt2 kinases have received much attention in the study of cancer because they are key mediators of the PI3K-signaling pathway, which is involved in the regulation of cell cycle, proliferation, apoptosis, protein synthesis and glucose metabolism." (PMID 28858257, 2017). "However, AKT2-addicted phenotypes observed in PTEN-depleted cancer cells suggest that alternate regulatory mechanisms may be at play." (PMID 28082369, 2017). "Thus, the development of selective inhibitors of Akt2 by targeting its PH domain may be worthwhile to obtain safer and more efficacious drugs to inhibit cell proliferation in cancer chemotherapy." (PMID 28036396, 2016). "However, the degree of functional redundancy between Akt1, Akt2, and Akt3 in cancer cell survival, proliferation and invasion remains unclear." (PMID 26234648, 2015). "Notably, our studies indicating that Akt2 opposes normal epithelial SC functions are apparently at odds with the notion that in a human immortalized breast cell line, Akt2 favors de novo formation of cancer SCs57-60." (PMID 32309540, 2013). "However, analogous activating mutations in AKT2 or AKT3 have not been identified in any cancer lineage." (PMID 18813315, 2008). "Molecular docking and Prime MM-GBSA screening of seventeen cancer-related protein targets, including Human Double Minute 2 protein (HDM2), DNA methyltransferase-1 (DNMT1), Protein Kinase B (AKT2), and Poly (ADP-ribose) polymerase 1 (PARP-1), were conducted." (PMID 40575462, 2025). "Non-synonymous SNPs (nsSNPs) in AKT2, a key kinase in the PI3K/AKT signaling pathway, can impact protein structure and function, leading to reduced efficacy of targeted cancer therapies." (PMID 41144441, 2025). "Alterations in genes such as PIK3R1 and AKT2 suggest hyperactivation of the PI3K/AKT pathway, which plays a critical role in promoting cancer cell survival, proliferation, and drug resistance." (PMID 39925800, 2025).